GSTM1 (glutathione S-transferase mu 1)
Diseases named in the same sentence as GSTM1 in open-access papers (continued):
Sharing a sentence is not in itself a finding about the gene and the disease.
injury (1 paper, 2012). Damage inflicted on the body as the direct or indirect result of an external force, with or without disruption of structural continuity. "It is speculated that people with null GSTM1 or GSTT1 genotypes could not detoxify the toxic reactive metabolites efficiently, and thus have higher risk of drug-induced liver injury and many cancers." (PMID 23082213, 2012).
juvenile open angle glaucoma (1 paper, 2019). Juvenile glaucoma (JG) is a rare autosomal dominant open angle glaucoma, characterized by early onset, severe elevation of intra ocular pressure of rapid progression, leading to optic nerve excavation and, when untreated, substantial visual impairment. "Similarly, the GSTM1 null genotype but not the GSTT1 null genotype may be linked to the risk of juvenile open-angle glaucoma (JOAG)." (PMID 30617052, 2019).
learning disabilities (1 paper, 2025). "Reported genetic variants associated with tobacco smoke metabolite processing (maternal CYP1A1, GSTT1, GSTM1, and norepinephrine transporter gene SLC6A2913) may influence polymorphisms in norepinephrine and dopamine transporter genes in offspring, increasing the risk of learning disabilities." (PMID 41445786, 2025).
leprosy (1 paper, 2012). Leprosy is a chronic infectious disease affecting primarily the skin and peripheral nervous system. "Allele and genotype distributions of CYP2E1 and GSTM1 genes within two samples from leprosy patients and healthy individuals." (PMID 23077626, 2012). "We investigated the possible effects of CYP2E1 and GSTM1 polymorphisms in 71 leprosy patients and in 110 individuals from the general population." (PMID 23077626, 2012). "Taken together, our results suggest that the CYP2E1*5, CYP2E1*6 and GSTM1*0 alleles may be considered as susceptibility markers for leprosy, and their distribution should be further investigated, as their presence seems to confer protection from M. leprae." (PMID 23077626, 2012). "In leprosy patients, the GSTM1*0 and CYP2E1*5 alleles and the combined alleles GSTM1*0/CYP2E1*6 and GSTM1*0/CYP2E1*5 were significantly related to a baciloscopic index (BI) (BI<3), while the CYP2E1*6 allele was related to a better clinical evolution in the leprosy spectrum." (PMID 23077626, 2012). "Therefore, GSTM1*0, CYP2E1*5 and CYP2E1*6 may be possible protection factors for leprosy patients." (PMID 23077626, 2012).
liver dysfunctions (1 paper, 2024). "Alcohol-reduced miR-743a-3p directly contributed to the upregulation of GSTM1, since liver specific silencing miR-743a-3p enhanced GSTM1 and miR-743a-3p loss protected alcohol-induced liver dysfunctions, which was significantly blocked by GSTM1 knockdown." (PMID 38475733, 2024).
lupus nephritis (1 paper, 2016). Glomerulonephritis in the context of systemic lupus erythematosus. "In conclusion, our study showed that polymorphims of the GSTM1 and GSTP1 could impact remission and ADRs in lupus nephritis treated with CYC." (PMID 27002825, 2016).
lymph node metastasis (1 paper, 2018). "In patients with GSTM1 polymorphism, lymph node metastasis was associated with pN1 vs. pN2 (pN classification; p = 0.036), suggesting that this polymorphism may affect tumor stage." (PMID 29765533, 2018). "In our study, GSTM1 polymorphism was associated with lymph node metastasis (pN calssification; p = 0.036), suggesting that this gene may influence tumor stage." (PMID 29765533, 2018).
Menorrhagia (1 paper, 1994). Prolonged and excessive menses at regular intervals in excess of 80 mL or lasting longer than 7 days. "We found that the frequency of GSTM1 null in the menorrhagia and case groups was not significantly different." (PMID 7917923, 1994).
mesothelioma (1 paper, 2009). A usually malignant and aggressive neoplasm of the mesothelium which is often associated with exposure to asbestos. "Down-regulation of GSTM1 is a novel finding in mesothelioma, and its role in mesothelioma susceptibility should be evaluated." (PMID 19662092, 2009).
metastatic cancer (1 paper, 2017). A carcinoma which has spread from the original site of growth to another anatomic site. "Thus, this is the first study to find the null genotypes of GSTT1 and GSTM1 significantly contribute to poorer OS compared with the present genotypes in MBC, which is quite different from the results in EBC setting, but in accordance with the findings in other metastatic cancer types." (PMID 29285301, 2017).
methamphetamine dependence (1 paper, 2015). A drug dependence that is a psychological dependency on the regular use of methamphetamine. "The aim of the present study is to investigate the association between GSTM1 and GSTT1 polymorphisms and methamphetamine dependence." (PMID 27843993, 2015). "The present study revealed that genetic polymorphisms of GSTT1 and GSTM1 are not risk factors for methamphetamine dependence." (PMID 27843993, 2015). "Neither GSTM1 (OR=0.92, 95% CI: 0.52-1.61, P=0.771) nor GSTT1 (OR=0.71, 95% CI: 0.33-1.54, P=0.381) null genotypes were significantly associated with risk of methamphetamine dependence." (PMID 27843993, 2015). "The combination genotypes of the GSTM1 and GSTT1 polymorphisms revealed that the genotypes of these two polymorphisms had no additive effect in relation to the susceptibility to methamphetamine dependence." (PMID 27843993, 2015).
nonalcoholic fatty liver (1 paper, 2020). "For example, in one study, GSTM1-null and GSTP1 Val allele genotypes, were found to increase the risk of nonalcoholic fatty liver in the Iranian population." (PMID 33083304, 2020).
occupational asthma (1 paper, 2022). Asthma attacks caused, triggered, or exacerbated by OCCUPATIONAL EXPOSURE. "We examined whether the genotypes of the GSTM1 and GSTT1 genes are associated with TDI-induced occupational asthma (TDI-OA)." (PMID 35186174, 2022).
pancreatitis (1 paper, 2025). Inflammation of the pancreas. "Interestingly, Gstm1 expression was significantly higher in knockout mice at baseline and at 8 hours after pancreatitis induction." (PMID 40907666, 2025).
Parkinsonism (1 paper, 2016). Characteristic neurologic anomaly resulting from degeneration of dopamine-generating cells in the substantia nigra, a region of the midbrain, characterized clinically by shaking, rigidity, slowness of movement and difficulty with walking and gait. "In our study, in PD patients with NFE2L2 variants (117E and 141H), we observed the effects of the NFE2L2 variants on its downstream gene expression including GSTM1 and SOD1, a major antioxidant enzyme in Parkinsonism." (PMID 26887053, 2016).
pharyngeal cancer (1 paper, 2008). "The results suggest that exon 4 mEH and GSTM1 null polymorphisms might influence oral and pharyngeal cancer." (PMID 19259333, 2008). "In the present case-controlstudy, we aimed to examine the relationship between the CYP1A1 Ile/Val, exon 4 mEH(139 Arg → His), and GSTM1 nullgenetic polymorphism and the risk of oral and pharyngeal cancers, investigatingalso the association with smoking, drinking, and the gene-gene interactions." (PMID 19259333, 2008). "As a conclusion, itseems that even though none of the three genotypes analysed have a significantassociation with the risk of oral and pharyngeal cancer in this population, therisks of tobacco and alcohol consumption might be modified by GSTM1 null andexon 4 mEH polymorphisms." (PMID 19259333, 2008).
polycythemia vera (1 paper, 2025). "In the Jordanian population, the GSTM1 null genotype alone and in combination with the CYP1A1 m1 genotype may be predisposing risk factors for polycythemia vera." (PMID 40357364, 2025).
polyposis (1 paper, 2019). "We first performed a meta-analysis to study the genetic relationships between the present/null polymorphisms of the GSTM1 and GSTT1 genes and the risk of polyposis." (PMID 30617052, 2019).
pulmonary hypertension (1 paper, 2024). Increased pressure within the pulmonary circulation due to lung or heart disorder. "An absence of both GSTM1 and GSTT1 genes was significantly associated with pulmonary hypertension." (PMID 38732015, 2024).
pulmonary tuberculosis (1 paper, 2018). A bacterial infection that affects the lungs and is caused by Mycobacterium tuberculosis. "A 2-fold ULN increased risk of elevation levels of ALT has been reported in individuals exhibiting the GSTM1 (−) allele among patients treated with isoniazid, rifampicin and pyrazinamide for pulmonary tuberculosis." (PMID 29523098, 2018).
rheumatic diseases (1 paper, 2022). "Deleting polymorphisms of glutathione S-transferase T1 (GSTT1) and M1 (GSTM1) genes influence the effectiveness of different drug combinations in a variety of rheumatic diseases." (PMID 36096831, 2022). "However, the possible influence of GSTM1 gene deletion polymorphism on bDMARD efficacy in JIA patients opens new horizons in investigations of GST gene polymorphisms and their influence on treatment outcomes in JIA and other rheumatic diseases." (PMID 36096831, 2022).
rosacea (1 paper, 2025). A chronic erythematous skin disorder that affects the face. "Additionally, null mutations in the GSTM1 and GSTT1 gene loci, which encode glutathione-S-transferase—an enzyme that catalyzes toxic oxidative intermediates—were more frequently observed in rosacea patients compared to the control group." (PMID 39859986, 2025).
uterine cancer (1 paper, 2023). Primary or metastatic malignant neoplasm involving the uterine corpus and/or the cervix. "Several relevant researches have illuminated GSTM1 gene polymorphism is nearlyassociated with the occurrence of cancers like GC and uterine cancer." (PMID 37814615, 2023).
Uterine leiomyoma (1 paper, 2013). The presence of a leiomyoma of the uterus. "We conclude that GSTM1 could be a potential biomarker for predicting or possible optimising the response to SPRMs treatment for the clinical management of uterine leiomyoma, which could save economic burden and impove quality of life for affectedwomen." (PMID 24324590, 2013). "Furthermore the finding could be useful to further explore GSTM1 as a biomarker for tailoring medical treatment of uterine leiomyomas for optimizing the response to treatment." (PMID 24324590, 2013).
cancer (172 papers, 1994 to 2026). A tumor composed of atypical neoplastic, often pleomorphic cells that invade other tissues. "In conclusion, GSTM1-null was associated with the overall increased cancer risks, especially in the lung, the bladder, the nasopharyngeal, the stomach and the cervical." (PMID 38579033, 2024). "GSTM1-null had significant associations with cancer risks (for smokers: OR = 1.347, 95% CI: 1.196–1.516, P < .001; for nonsmokers: OR = 1.423, 95% CI: 1.270–1.594, P < .001; for drinkers: OR = 1.748, 95% CI: 1.093–2.797, P = .02)." (PMID 38579033, 2024). "The overall finding showed significant statistical association was found between cancer risks and GSTM1-null in drinkers (I2 = 89.8%, OR = 2.33, 95% CI: 1.093–2.797, P = .02)." (PMID 38579033, 2024). "Polymorphism in other genes, such as N-acetyl metastases 2 (NAT2) and glutathione S-metastases (GSTM1) is also related to the increased cancer risk of RCC in the smokers." (PMID 38957811, 2024). "Integral analysis of the association between GSTM1 polymorphism and cancer risk among smoking and drinking populations." (PMID 38579033, 2024). "NAT2 and GSTM1 play a role in the breakdown and elimination of cancer-causing substances present in tobacco, thus forming the basis of this connection." (PMID 38957811, 2024). "Elevated expression of GSTM1-1 is associated with an impaired clinical response to therapies in a number of different types of cancer." (PMID 39125992, 2024). "Among the known isoenzymes of GST, the most studied polymorphisms in relation to cancers are the SNP in the GSTM1, GSTT1 and GSTP1 genes." (PMID 37819495, 2023). "Several reports proposed adding PC to the list of cancers for which smoking is a risk factor and investigated possible associations between GSTM1 and GSTT1 deficient genotypes and susceptibility to PC in smokers." (PMID 36824501, 2023). "In 1993, the first publication was reported on the association between GSTM1 null genotype and BC cancer susceptibility [Reference 1 in S1 Appendix]." (PMID 32155154, 2020). "Among the biomarkers of genetic susceptibility, only GSTM1 (glutathione S-transferase Mu 1 gene polymorphisms) was present in all those who died from cancer." (PMID 32218300, 2020). "In several cancers, the association between GSTM1 polymorphisms and cancer risk has been suggested through meta-analysis studies." (PMID 32545553, 2020). "Many studies have investigated the relationship between the genetic polymorphism of GSTM1 and the risk of cancer, but the association remains controversial among different populations." (PMID 31646988, 2019). "Concerning the GST genes, the individuals carrying deleted alleles (e.g. GSTT1 and GSTM1 null) are of special interest regarding the response to antineoplastic agents for cancer treatment." (PMID 31324178, 2019). "The use of healthy controls over hospital based controls was intentionally preferred to reduce possible bias in results due to the risk conferred by deletion polymorphism of GSTM1 and GSTT1to non-cancer diseases." (PMID 30034435, 2018). "The GSTM1 gene is located on chromosome 1p13.3 and genetic differences in the gene can affect an individual's predisposition to cancer, as well as the toxicity and effectiveness of some drugs." (PMID 29795558, 2018). "In GSTM1 the null variant is the most common polymorphism, which results in reduced enzymatic activity and has been associated with the development of cancers." (PMID 28508326, 2018). "A large body of evidence has shown that loss of GSTM1 increases the susceptibility to several types of cancer including lung and bladder." (PMID 27964748, 2016). "Few reports have linked the homozygous GSTT1∗0 genotype to increased cancer susceptibility, but an increased prevalence of the combined GSTM1 and GSTT1 null genotypes has been found among head and neck cancer patients." (PMID 27294127, 2016).
cancer (continued). "GSTM1 is also a key member of the GSTs superfamily and has previously been associated with increased cancer risk in as a homozygous deletion polymorphism in some ethnic groups." (PMID 27566576, 2016). "Similar to GSTM1, a dramatic increase in the cancer risk is associated with the GSTT1 polymorphism (null vs. present: OR = 1.16, 95%CI = 1.11–1.21, p<0.001)." (PMID 24250808, 2013). "Other studies of GSTM1 deletions have identified positive associations between the null genotype and a variety of cancers, included oral, colorectal, cervical, and bladder." (PMID 23637977, 2013). "Although there is little evidence of a link between cancer and the specific RAD23B, ERCC2, and GSTM1 variants identified here, previous studies have observed associations between one or more types of cancer and other variants on these three genes." (PMID 23637977, 2013). "Several studies correlate GSTM1 deletion with increased risk of cancer indicating is possible antiproliferative activity." (PMID 24324590, 2013). "In the present study, we examined the association between GSTM1 and GSTT1 null genotypes and cancer risk and assessed the multiplicative interactions among GSTM1, GSTT1, and smoking status." (PMID 24250808, 2013). "The null genotypes of GSTM1 and GSTT1 polymorphisms were associated with a significantly increased risk in cancer (for GSTM1: OR = 1.17; 95%CI = 1.14–1.21; for GSTT1: OR = 1.16; 95%CI = 1.11–1.21, respectively)." (PMID 24250808, 2013). "Overall, a significant increased risk of cancer is associated with the GSTM1 polymorphism (null vs. present: OR = 1.17, 95%CI = 1.14–1.21, p<0.001)." (PMID 24250808, 2013). "As one of the most important phase II enzymes, GSTM1 was known to abolish enzyme activities and therefore has been linked with an increase in a number of cancers, most likely due to increased susceptibilities to environmental toxins and carcinogens." (PMID 22900055, 2012). "Actually, a number of studies have demonstrated that GSTM1 null genotype is significantly associated with some other cancers only in Asians." (PMID 23071687, 2012). "There are numerous reports of association between GSTM1 null genotype and smoking in various cancers including esophageal, bladder colorectal and oral." (PMID 22206016, 2011). "Despite the small size of the study groups, our results substantiate the cancer risk predictivity of CA frequency, ruling against a strong modifying effect of GSTM1 and GSTT1 polymorphisms." (PMID 19270789, 2009). "Genotypes of glutathione S-transferase iso-enzyme GSTM1 gene deletion, has been associated with an increased risk of cancer at various sites." (PMID 17475007, 2007). "Several molecular studies have elucidated crucial insights into the association between GSTM1 and GSTT1 and cancer susceptibility, revealing that individuals harboring homozygous deletions in GSTM1 and GSTT1 genes lack GST-m and GST-q enzyme activity, respectively." (PMID 39619061, 2024). "In conclusion, GSTM1-null might increase the risk of cancers, whether alone or in combination with smoking, but smoking and drinking might significantly contribute to increased cancer risks associated with GSTT1-null." (PMID 38579033, 2024). "Taken together, these results imply that there is an association between cancer progression and GSTM1 gene copy number, which is in general agreement with our observation that the expression of other genes from GST family (GSTM2 and GSTT1) is also copy number dependent." (PMID 39726707, 2024). "Deletion of the GSTM1 gene can lead to inactivation of GSTM1-1, altering resistance to poisons and carcinogens, which can result in the loss of detoxification capacity and increase the risk of cancer development." (PMID 39125992, 2024). "As GSTM1 is crucial in the detoxification of external toxins from the body, individuals with deleted copies of this gene are at a higher risk for developing different types of cancer and other multifactorial diseases as well as drug related toxicities." (PMID 38409353, 2024).